CAB39 (calcium binding protein 39)
Description:
Component of a complex that binds and activates STK11/LKB1. In the complex, required to stabilize the interaction between CAB39/MO25 (CAB39/MO25alpha or CAB39L/MO25beta) and STK11/LKB1.
Synonyms: MO25; CGI-66
Tractability: Small molecule: a structure with a bound ligand is known; it has a binding pocket of medium quality. Antibody: its Gene Ontology location is reachable by antibodies, with high confidence. PROTAC: ubiquitination databases record sites on it; its protein half-life has been measured.
Gene: Protein-coding gene on chromosome 2 (230,712,822 to 230,821,076, forward strand). Ensembl gene ENSG00000135932.
Subcellular location: Cytoplasm
Subcellular location (Human Protein Atlas): Vesicles; Endoplasmic reticulum
Pathways (Reactome):
Immune System: Neutrophil degranulation
Signal Transduction: Energy dependent regulation of mTOR by LKB1-AMPK
Gene Ontology:
Molecular function: kinase binding; protein binding; protein kinase activator activity; protein serine/threonine kinase activator activity; protein serine/threonine kinase binding; signaling adaptor activity
Biological process: cellular hypotonic response; intracellular signal transduction; regulation of transmembrane transport
Cellular component: cytoplasm; extracellular exosome; serine/threonine protein kinase complex; cytosol; extracellular region; ficolin-1-rich granule lumen; secretory granule lumen
Genetic constraint (gnomAD): Loss-of-function variants: 5 observed, 15.17 expected, observed/expected ratio (o/e) 0.33, 90% interval 0.17 to 0.69. The upper end of that interval is the gene's LOEUF score, 0.69, which puts it in group 2 of 6, group 1 being the genes least tolerant of losing a copy. Missense variants: 107 observed, 185.93 expected, observed/expected ratio (o/e) 0.58, 90% interval 0.49 to 0.68. Synonymous variants: 71 observed, 66.89 expected, observed/expected ratio (o/e) 1.06, 90% interval 0.88 to 1.29.
Homologues: Orthologues: chimpanzee CAB39 (100% identical), guinea pig CAB39 (99% identical), macaque CAB39 (99% identical), dog CAB39 (99% identical), pig CAB39 (99% identical), rabbit CAB39 (99% identical), mouse Cab39 (99% identical), tropical clawed frog cab39 (99% identical), zebrafish cab39 (93% identical), rat Cab39 (91% identical), Drosophila melanogaster Mo25 (70% identical), Caenorhabditis elegans mop-25.1 (65% identical), and 1 more. Paralogues in human: CAB39L (80% identical).